HAS2 (hyaluronan synthase 2)
Diseases named in the same sentence as HAS2 in open-access papers (continued):
Sharing a sentence is not in itself a finding about the gene and the disease.
pancreatic cancer (continued). "The expression of SPHK1 and HAS2 was markedly upregulated in pancreatic cancer tissue and cell lines, respectively." (PMID 33506044, 2021). "We have verified that the expression of SPHK1 and HAS2 was markedly increased in pancreatic cancer tumor tissues." (PMID 33506044, 2021). "In this study, we analyzed the expression and clinical significance of SPHK1 and HAS2 in pancreatic cancer." (PMID 33506044, 2021). "The results showed that SPHK1 and HAS2 expressions were increased in pancreatic cancer tissues compared with normal tissues." (PMID 33506044, 2021). "The results showed that the mRNA expression of SPHK1 and HAS2 was significantly higher in pancreatic cancer group (177 cases) than those of the healthy control (173 cases) (P < 0.05 and P < 0.05), respectively." (PMID 33506044, 2021). "Similar to our finding in this study, a recent study demonstrated that Etv1 enhances Has2 expression in pancreatic cancer and alters the tumor microenvironment." (PMID 31109321, 2019). "The role of hyaluronan synthases 2 and 3 (HAS2, 3) was investigated in pancreatic cancer growth and the tumor microenvironment." (PMID 25147816, 2014). "We demonstrate, for the first time, that expression patterns of HA and its regulators (HAS2 and HYAL1) are significantly associated with survival of patients with pancreatic cancer." (PMID 24244714, 2013). "In the present study, we demonstrated a relationship between increased expression of HAS2 and poor prognosis in pancreatic cancer." (PMID 24244714, 2013). "HAS2 is well known in various tumor invasions, so the interaction of SPHK1 and HAS2 might exert a pivotal role in pancreatic cancer progression." (PMID 33506044, 2021). "The common signaling pathway of SPHK1 and HAS2 in pancreatic cancer might be responsible for cancer progression." (PMID 33506044, 2021). "The possible correlation between SPHK1 and HAS2 expressions in pancreatic cancer was also analyzed." (PMID 33506044, 2021). "Additionally, Spearman correlation analysis was applied to assess the correlation between the SPHK1 and HAS2 in pancreatic cancer." (PMID 33506044, 2021). "The increased expression of SPHK1 and HAS2 in pancreatic cancer implied that SPHK1 and HAS2 may be essential for the progression of pancreatic cancer." (PMID 33506044, 2021). "Therefore, we analyzed TCGA and GTEx databases to evaluate the expression of SPHK1 and HAS2 in pancreatic cancer." (PMID 33506044, 2021). "Therefore, it is clinically possible to detect SPHK1 and HAS2 to improve the diagnosis and prognosis of pancreatic cancer." (PMID 33506044, 2021). "The results of GO and KEGG analyses suggested that SPHK1 and HAS2 might play important roles in pancreatic cancer cell proliferation and invasion." (PMID 33506044, 2021). "Furthermore, the potential prognostic roles of SPHK1 and HAS2 in pancreatic cancer patients were evaluated." (PMID 33506044, 2021). "However, the expression of SPHK1 and HAS2 was more easily detected in the advanced stages of pancreatic cancer." (PMID 33506044, 2021). "Interestingly, a previous study used gene expression profiling to demonstrate that HAS2 expression is up-regulated in stromal fibroblasts in response to co-culture with pancreatic cancer cells." (PMID 24244714, 2013). "Thus, SPHK1 and HAS2 might be useful prognostic biomarkers for pancreatic cancer and worthy of further study before their use in clinical practice." (PMID 33506044, 2021). "Overexpression of SPHK1 and HAS2 could be important markers for the prognosis of pancreatic cancer." (PMID 33506044, 2021). "However, there is no study on the association between HAS2 expression and the progression of pancreatic cancer." (PMID 33506044, 2021).
pancreatic cancer (continued). "In another study, the presence of stromal fibroblasts increased pancreatic cancer cell expression of a set of genes linked to tumor cell invasion, including cyclooxygenase 2 (COX-2)/prostaglandin-endoperoxide synthase 2 (PTGS2), hyaluronan synthase 2 (HAS2), and matrix metalloproteinase-1 (MMP-1)." (PMID 29903049, 2018). "In pancreatic cancer with a high ETV1 expression, the matricellular protein SPARC and the Hyaluronan Synthase 2 are two ETV1‐downstream targets responsible for its role in invasion and metastasis." (PMID 40275610, 2025). "According to the median values of SPHK1 and HAS2 expressions, pancreatic cancer patients were divided into high and low SPHK1 and HAS2 expression groups." (PMID 33506044, 2021). "To further verify the expression of SPHK1 and HAS2 in pancreatic cancer, we detected the mRNA and protein expressions of SPHK1 and HAS2 in pancreatic cancer cell lines." (PMID 33506044, 2021). "Thus, we consider that SPHK1 and HAS2 may be potential biomarkers for pancreatic cancer diagnosis." (PMID 33506044, 2021). "HAS2 and HAS3 were found to produce extracellular HA, and HAS2 appears to contribute to cytoplasmic HA production when HAS2 is overexpressed in pancreatic cancer cells." (PMID 29137675, 2017). "In this study, we explored the biological consequences of HAS2 and HAS3 overexpression in BxPC-3 pancreatic cancer cells and in xenograft tumor models." (PMID 25147816, 2014). "The present study demonstrated significant correlations between increased expressions of HA and HAS2, and decreased expression of HYAL1 and poor prognosis in patients with resected pancreatic cancer." (PMID 24244714, 2013). "Notably, in the present study, three pancreatic cancer cell lines were selected for evaluating the SPHK1 and HAS2 expressions." (PMID 33506044, 2021). "Our data showed that the epithelioid-derived PANC-1 expressed more SPHK1 and HAS2, compared to these metastatic site-derived Capan-1 and AsPC1, suggesting that SPHK1 and HAS2 may be related to the origin of pancreatic cancer cell lines." (PMID 33506044, 2021). "The results revealed that pancreatic cancer patients with high expression of SPHK1 had shorter OS than patients with low SPHK1 expression (P = 0.037), and pancreatic cancer patients with high HAS2 expression had shorter OS than patients with low expression of HAS2 (P = 0.0074)." (PMID 33506044, 2021). "ZEB1correlates negatively with ESRP1 and positively with HAS2 in NCI-60 and CCLE cellline cohorts and in lung, breast, and pancreatic tumors, indicating that feedback loops operatingamong ZEB1, ESRP1, and HAS2 may modulate cancer cell plasticity across subtypes." (PMID 31069317, 2018). "However, it should be noted that SPHK1 and HAS2 might not be sensitive in the early diagnosis of pancreatic cancer." (PMID 33506044, 2021). "Thus, SPHK1 and HAS2 might not be ideal biomarkers in the detection of early-stage pancreatic cancer." (PMID 33506044, 2021). "Unlike HA and HAS2, decreased expression of HYAL1 correlated with poor survival in our present series of pancreatic cancer." (PMID 24244714, 2013).
liver fibrosis (14 papers, 2019 to 2025). "Due to its association with extracellular matrix-producing HSCs and liver fibrosis, HAS2 is an attractive target for antifibrotic therapies." (PMID 35662287, 2022). "To evaluate the causality of HA in liver fibrosis, we first tested whether forced expression of Has2, which would increase HA production, aggravates liver fibrosis." (PMID 40475534, 2025). "We previously determined that in liver fibrosis, HA is produced from activated HSCs through the upregulation of HA synthase 2 (HAS2)." (PMID 39946200, 2025). "Genetic suppression of HAS2, through small interfering RNA (siRNA) or miR-200c modulation, has been shown to attenuate liver fibrosis and HA deposition in murine models." (PMID 41155434, 2025). "The functional annotation of enriched genes revealed that 4MU and HAS2 knockdown can suppress the ER stress response induced by CCl4 in mice with liver fibrosis." (PMID 38307876, 2024). "Together, these findings demonstrate that 4MU treatment and HAS2 knockdown inhibit angiogenesis in hepatic fibrosis." (PMID 38307876, 2024). "In our previously published work, we showed that 4MU inhibits HAS2 expression and hyaluronan deposition in liver parenchyma during the development of liver fibrosis in mice." (PMID 36768453, 2023). "A recent study established a connection between enhanced HA synthesis and HAS2 overexpression in activated HSCs during liver fibrosis." (PMID 36930869, 2023). "High levels of HA, especially low-molecular-weight HA (LMW-HA, 100–300 kDa), are found in the serum and liver of patients and animals with liver fibrosis, and both HAS2 and HA promote HSC activation and fibrosis." (PMID 35662287, 2022). "Here, we demonstrated that downregulation of miR-200c contributes to the progression of liver fibrosis by regulating HAS2 expression posttranscriptionally." (PMID 35662287, 2022). "We previously identified hyaluronan synthase 2 (HAS2) as a driver of liver fibrosis and hepatic stellate cell (HSC) activation." (PMID 35662287, 2022). "Here, we report a novel signaling axis involving miR-200c, HAS2, and inflammatory chemokines that contributes to liver fibrosis." (PMID 35662287, 2022). "Developing strategies to suppress HSC activation is key to alleviating liver fibrosis, and HAS2 is an attractive candidate for intervention." (PMID 35662287, 2022). "To identify the miRNA(s) responsible for the upregulation of HAS2 in liver fibrosis, we searched TargetScan 7 for putative miRNAs that target HAS2." (PMID 35662287, 2022). "As miR-200c was the most likely regulator of HAS2 in the fibrotic liver, we focused our subsequent investigation on the signaling network that connects TGF-β, miRNA, HAS2, and liver fibrosis." (PMID 35662287, 2022). "Here, we explored the therapeutic potential of HAS2 inhibition in acute liver injury and liver fibrosis." (PMID 35662287, 2022). "A study showed that HAS2 regulation of hyaluronan synthesis was important for liver fibrosis development." (PMID 33892667, 2021). "In the initial stage of the disease, the expression of hepatic HA synthase 2 (HAS2) is markedly up regulated by transforming growth factor–β in activated hepatic stellate cells (HSCs) and in murine and human liver fibrosis." (PMID 34202190, 2021). "Recently, hyaluronic acid has been directly involved in the development of liver fibrosis, with hyaluronan synthase 2 (HAS2) having a central role in the production of HA, activation of hepatic stellate cells (HSCs) and in the progression of liver fibrosis." (PMID 34202190, 2021). "Hyaluronan synthase 2-mediated glycocalyx hyaluronan (HA) production mediates liver fibrosis." (PMID 37434162, 2023). "We then examined the role of HSC-derived Has2 in CCl4-induced liver fibrosis." (PMID 35662287, 2022).
liver fibrosis (continued). "During liver fibrosis, HAS2 expression is substantially induced in HSCs15." (PMID 35662287, 2022). "Furthermore, HA expression and liver fibrosis were reduced upon HAS2 inhibition and enhanced upon HAS2 overexpression in HSCs." (PMID 34440218, 2021). "HAS2 mediated hyaluronan production through Notch1 activation and liver fibrosis." (PMID 33506044, 2021). "HA and HA synthase 2 (HAS2) expression was elevated in both human and murine liver fibrosis." (PMID 34440218, 2021). "HAS2 expression is elevated in human and murine liver fibrosis." (PMID 31718044, 2019). "Furthermore, we show that successful treatment of liver fibrosis may be achieved with small molecule HAS2 inhibitors, which underpins the viability of repurposing 4MU as an antifibrotic agent." (PMID 38307876, 2024). "After establishing the direct interaction between miR-200c and HAS2, we investigated the functional outcome of regulating HAS2 expression in three murine models: CCl4-induced acute liver injury, CCl4-induced chronic liver fibrosis, and bile duct ligation-induced liver fibrosis." (PMID 35662287, 2022). "During the progression of liver fibrosis, HA accumulation is primarily driven by the activation of hepatic HSCs, which upregulate HAS, particularly HAS2, in response to profibrogenic cues such as TGF-β, oxidative stress, and hypoxia." (PMID 41155434, 2025). "HAS3 knockout mice develop liver fibrosis similar to wild-type mice, suggesting that HAS1 or HAS2 is more likely to regulate liver fibrosis." (PMID 36930869, 2023). "In mice lacking Has2, both HA and liver fibrosis levels were reduced; conversely, mice overexpressing Has2 overproduced HA, promoting HSC activation and exacerbating liver fibrosis." (PMID 34202190, 2021). "TGF-β-HAS2-HA: Seki and coworkers delineated another downstream route of TGF-β mediated HSC activation in liver fibrosis, which ends in hyaluronan (HA) production, a major ECM glycosaminoglycan, and biomarker of liver cirrhosis." (PMID 31718044, 2019). "In contrast to these well-defined transcriptional networks, the posttranscriptional regulation of HAS2 in liver fibrosis has not been elucidated." (PMID 35662287, 2022). "In liver fibrosis, WT1 binds to the HAS2 promoter and stimulates the transcription of HAS215." (PMID 35662287, 2022). "Furthermore, HA production and liver fibrosis were decreased upon HAS2 depletion in HSC and enhanced upon HAS2 overexpression." (PMID 31718044, 2019). "However, the miRNA-mediated regulation of HAS2 in liver fibrosis has not been elucidated." (PMID 35662287, 2022).
lung carcinoma (12 papers, 2017 to 2025). "Depletion of ITIH2 and HAS2 reduced HA matrix formation and the migration and invasion of lung cancer cells." (PMID 40178908, 2025). "A study in colorectal, osteosarcoma, and lung cancer cell lines showed that irradiation induced the expression of HAS2, resulting in their radioresistance, one of the hallmarks of the CSC47." (PMID 30858465, 2019). "A previous study studying HA CD44/RHAMM pathway in lung cancer cells only knocked down HAS2 and HAS3 as us, we suggested they might also come across the same issue." (PMID 33407495, 2021). "HAS2-mediated cancer progression was also indicated in lung cancer and squamous cell carcinoma." (PMID 32862195, 2021). "Our scrutiny of 13 murine lung cancer cell lines and TCGA-LUAD data disclosed a positive correlation between ZEB1 and HAS2 mRNA levels, solidifying ZEB1’s role as a transcription activator for HAS2, an HA synthase." (PMID 40178908, 2025). "Within the HA synthase family, Has2 exhibited the highest expression and proved to be under the regulatory influence of ZEB1 in murine lung cancer cells." (PMID 40178908, 2025). "Recent studies have demonstrated the possible potential molecular pathways for SPHK1 and HAS2 in cancer progression, one of which is that SPHK1 induces lung cancer cell migration and paclitaxel resistance by modulating IGF-1-induced EMT." (PMID 33506044, 2021). "Lymphocyte-EC interactions with respect to lymphocyte recruitment and homing pathways, such as ICAM1/2-integrin and HAS2/MMP7-CD44, were enriched in early stages of lung cancer nodules compared to advanced lung cancer, indicating that EC remodels lymphocytes in the direction of immunosuppression." (PMID 37187731, 2023). "We determined the expression level of HAS2, HAS3, CD44, and RHAMM in lung cancer cell lines except for CD44 in H1975 and HAS2 in H460 which might be too low to be detected in our experiment." (PMID 33407495, 2021). "Thus, HAS2 and USP17 are significantly induced in lung carcinomas, in particular in ADC (P<0.005)." (PMID 28604766, 2017). "Importantly, high levels of USP17 and HAS2 were detected in a panel of cancer cell lines compared to normal cells, and immunohistochemical stainings revealed higher expression of USP17 and HAS2 in tissues of lung cancer patients compared to normal tissue." (PMID 28604766, 2017). "Moreover, genome-wide transcript analysis of tumor samples confirmed a close correlation between ZEB1 and HAS2 (but not with HAS1 and HAS3) in breast, pancreas and lung cancer specimens (GSE42568, GSE28735 and GSE41271)." (PMID 28086235, 2017).